GLRA2 (glycine receptor alpha 2)
Description:
Subunit of heteromeric glycine-gated chloride channels. Plays a role in synaptic plasticity (By similarity). Contributes to the generation of inhibitory postsynaptic currents, and is involved in the down-regulation of neuronal excitability. Plays a role in cellular responses to ethanol.
Synonyms: GLR; MRXSP
Tractability: Small molecule: a structure with a bound ligand is known; a high-quality ligand is known; it belongs to a druggable protein family. Antibody: UniProt places it where antibodies can reach, with high confidence; its Gene Ontology location is reachable by antibodies, with high confidence; UniProt predicts a signal peptide or a membrane-spanning region. PROTAC: its protein half-life has been measured; a small molecule that binds it is known.
Target class: Ion channel; Ligand-gated ion channel; Glycine receptor
Gene: Protein-coding gene on chromosome X (14,529,298 to 14,731,812, forward strand). Ensembl gene ENSG00000101958.
Subcellular location: Postsynaptic cell membrane; Synapse; Cell membrane; Cell projection
Subcellular location (Human Protein Atlas): Plasma membrane; Vesicles
Pathways (Reactome):
Neuronal System: Neurotransmitter receptors and postsynaptic signal transmission
Gene Ontology:
Molecular function: extracellularly glycine-gated chloride channel activity; glycine binding; glycine-gated chloride ion channel activity; excitatory extracellular ligand-gated monoatomic ion channel activity; extracellular ligand-gated monoatomic ion channel activity; monoatomic ion channel activity; transmembrane signaling receptor activity; transmitter-gated monoatomic ion channel activity; transmitter-gated monoatomic ion channel activity involved in regulation of postsynaptic membrane potential
Biological process: cellular response to amino acid stimulus; cellular response to ethanol; cellular response to zinc ion; chloride transmembrane transport; monoatomic ion transmembrane transport; neuropeptide signaling pathway; chloride transport; excitatory postsynaptic potential; modulation of chemical synaptic transmission; monoatomic ion transport; regulation of postsynaptic membrane potential
Cellular component: plasma membrane; glycinergic synapse; postsynaptic membrane; synapse; GABA-ergic synapse; membrane; postsynaptic specialization membrane
Homologues: Orthologues: dog GLRA2 (99% identical), chimpanzee GLRA2 (99% identical), macaque GLRA2 (99% identical), guinea pig GLRA2 (99% identical), rabbit GLRA2 (99% identical), rat Glra2 (99% identical), mouse Glra2 (99% identical), pig GLRA2 (99% identical), tropical clawed frog glra2 (93% identical), zebrafish glra2 (82% identical). Paralogues in human: GLRA3 (78% identical), GLRA1 (76% identical), GLRB (48% identical), GABRB3 (38% identical), GABRB2 (37% identical), GABRB1 (37% identical), GABRA1 (36% identical), GABRA2 (36% identical), GABRA4 (36% identical), GABRG3 (36% identical), GABRA6 (35% identical), GABRQ (35% identical), and 33 more.
Diseases named in the same sentence as GLRA2 in open-access papers:
GLRA2 is named in the same sentence as 20 diseases in open-access papers, as found by Europe PMC text mining. Sharing a sentence is not in itself a finding about the gene and the disease. The quoted sentences say what the papers report.
autism spectrum disorder (7 papers, 2017 to 2025). A spectrum of developmental disorders that includes autism, and Asperger syndrome. "Mutations in GLRA2 are involved in the pathogenesis of autism spectrum disorder – a pathological condition characterized by deficits in social interaction and repetitive patterns of behavioral output." (PMID 29375305, 2017). "Mutations in GLRA1 underlie development of hyperekplexia – a rare congenital human motor disorder; several mutations in GLRA2 have been linked to autism spectrum disorder, and GLRA3 has been implicated in the pathogenesis of temporal lobe epilepsy." (PMID 29375305, 2017). "In humans, rare variants in GLRA2, which is located on the X chromosome, are associated with autism spectrum disorder (ASD) in the hemizygous state in males." (PMID 28588452, 2017). "The described mechanism might shed light on the pathophysiological mechanisms in GLRA2-linked autism spectrum disorder cases." (PMID 30374290, 2018). "Mutations in GLRA2 are associated with autism spectrum disorder, but the underlying pathophysiology is not described yet." (PMID 30374290, 2018).
autism (6 papers, 2017 to 2022). Persistent deficits in social interaction and communication and interaction as well as a markedly restricted repertoire of activity and interest as well as repetitive patterns of behavior. "GLRA2 is a glycine receptor involved in neurodevelopment in which variants are implicated in autism, including a patient with comorbid epilepsy." (PMID 31190668, 2019). "We report the functional characterization of a third missense variant in GLRA2 (p.R323L), associated with autism, macrocephaly, epilepsy and hypothyroidism in a female proband." (PMID 28588452, 2017). "In this respect, the Glra2-KO mouse line might be utilized as an animal disease model to better understand the pathophysiology of autism at the cellular and network level." (PMID 29375305, 2017).
microcephaly (3 papers, 2017 to 2025). A congenital or acquired developmental disorder in which the circumference of the head is smaller than normal for the person's age and sex. "However, deletion of Glra2 causes a moderate microcephaly in newborn mice and disrupts the functional organization of the cerebral cortex, which corresponds to an impaired long-term potentiation in the prefrontal cortex and deficits in object recognition memory." (PMID 29375305, 2017). "This resulted in a reduction of projection neurons in upper or deep layers of the cerebral cortex and moderate microcephaly in newborn Glra2 knockout mice." (PMID 28588452, 2017). "Disruption of the GlyR α2 subunit gene (Glra2) in mice leads to disrupted dorsal cortical progenitor homeostasis, leading to a depletion of projection neurons and moderate microcephaly in newborn mice." (PMID 28588452, 2017). "This case was of interest, given that microcephaly was observed in newborn Glra2 knockout mice." (PMID 40007572, 2025).
Anxiety (2 papers, 2014 to 2017). Intense feelings of nervousness, tension, or panic often arise in response to interpersonal stresses. "This indicates that basic locomotion, habituation, and level of anxiety are not affected in Glra2-KO animals." (PMID 29375305, 2017). "At this time, there is no sufficient research linking the Glra2 gene with PTSD, anxiety, or mood disorders." (PMID 25165739, 2014).
cobalamin deficiency (1 paper, 2021). "Genes related to stress response (ceremide kinase like) and nutrient metabolism (phosphoenolpyruvate carboxy-kinase 1, methylmalonic aciduria [cobalamin deficiency] cblB type, glycine receptor alpha 2, solute carrier family 7 member 11, etc.)were also identified to be differentially expressed." (PMID 33152221, 2021).
ischemia (1 paper, 2025). A hypoperfusion of the BLOOD through an organ or tissue caused by a PATHOLOGIC CONSTRICTION or obstruction of its BLOOD VESSELS, or an absence of BLOOD CIRCULATION. "Namely, the peptide reduced the expression of many genes (e.g., P2rx6, Gabra3, Grik4, Oprl1, Glra2, Crhr1, Hrh1, Chrm5, Grik1) related to the neurosignaling system and whose expression was not significantly changed by ischemia itself." (PMID 40650034, 2025).
myocardial infarction (1 paper, 2022). Gross necrosis of the myocardium, as a result of interruption of the blood supply to the area, as in coronary thrombosis. "As a result, AKAP12 and GLRA2 may have a role in the progression of myocardial infarction by affecting cardiac contractility." (PMID 36499335, 2022).
Stroke (1 paper, 2024). Sudden impairment of blood flow to a part of the brain due to occlusion or rupture of an artery to the brain. "Glycine attenuates cerebrovascular remodeling via glycine receptor alpha 2 and vascular endothelial growth factor receptor 2 after stroke." (PMID 38958365, 2024).
neurological disease (2 papers, 2019 to 2022). "Interestingly, aside from the 3 ́UTR variant in GLRA2, none of the de novo variants in the Epi4k participants with MACF1 CH variants are in genes associated with neurological disease or predicted with confidence to have a negative impact on gene function." (PMID 31190668, 2019).
cancer (1 paper, 2018). A tumor composed of atypical neoplastic, often pleomorphic cells that invade other tissues. "First, we tested for expression of GLRA2 mutually exclusive exon 3A and 3B usage in HeLa and H1299 cancer cells, and observed that exon 3B of GLRA2 was preferentially used in cancer cells." (PMID 30082712, 2018). "Next, we looked in our H1299 NOVA1 rescue series to see if GLRA2 was regulated by NOVA1 in cancer cells and indeed found that GLRA2 exon 3B is preferentially used when NOVA1 levels are higher similar to previous studies." (PMID 30082712, 2018).
GLRA2 also shares sentences with these, for which no sentence is quoted: epilepsy (6 papers); developmental delay (1); hypothyroidism (1); Intellectual disability (1); language delay (1); Methylmalonic aciduria (1); mood disorder (1); myopia (1); neurodevelopmental disorder (1); neuronal migration disorders (1).